CD4 (CD4 molecule)
Diseases named in the same sentence as CD4 in open-access papers (continued):
Sharing a sentence is not in itself a finding about the gene and the disease.
COVID-19 (continued). "Higher percentages of CD4+ T cells producing IFNγ, TNFα, IL-2, and IL-17A and CD8+ T cells producing IL-2 and IL-17A have been detected by flow cytometry in PBMCs from COVID-19 patients vs. healthy controls after in vitro stimulation." (PMID 33634100, 2020). "Meanwhile, we found that the lymphocytes, monocytes, CD3+, CD4+, CD8+, CD19+ T cells and P/F ratio were protective factors (OR < 1) for COVID-19 patients." (PMID 32633729, 2020). "SARS-CoV-2-specific CD4 T cells produce IL-2 and IFN-γ, suggesting that COVID-19-recovered individuals exhibit a TH1 cell response." (PMID 33262993, 2020). "This violent assault can be seen in patients with severe disease who's plasma levels of IL-6, TNFα, and IL-10 are higher, and circulating CD4 and CD8 T cells are lower than patients with mild COVID-19 or healthy controls." (PMID 32793615, 2020). "We assessed SARS-CoV-2 specific CD8+ and CD4+ T cell responses to the Nucleocapsid (N), Membrane (M) and Spike (S) proteins, the three principal targets of CD8+ and CD4+ T cell responses in COVID-19-infected individuals." (PMID 33488630, 2020). "And importantly, lymphocytes, especially CD3+, CD4+, and CD8+ T cells in the peripheral blood of COVID-19 patients, which was relevant with serum LDH, were also dynamically correlated with the severity of the disease." (PMID 32633729, 2020). "SARS-CoV-2-specific CD4 and CD8 T cells have been shown to be present in individuals with acute, mild, and asymptomatic Coronavirus disease (COVID-19)." (PMID 35047875, 2020). "Overall, acute COVID-19 and malaria infection resulted in a comparably elevated activation and altered differentiation status of the CD8+ and CD4+ T cell populations." (PMID 32983106, 2020). "PLWHA who were old, had low CD4+ T lymphocyte count, infected HIV through homosexual activity, and had been diagnosed for HIV for a long time, were more likely to develop COVID-19." (PMID 32818208, 2020). "Top genes include IL1A15 and other components of the innate and adaptive immune systems (such as CXCL10, CD4 and TLR3), which have previously been shown to contribute to COVID-19 pathogenesis." (PMID 33339864, 2020). "Sorting of the immune cell population in COVID-19 patients revealed the presence of hyperactivated T-cells with high fractions of HLA-DR+, CCR6+ Th17 CD4+ and CD38+ CD8+/CD4+ T-cells." (PMID 32645974, 2020). "In conclusion, the data we observed support a specific role of CD4 T lymphocytes in early stages and a potential implication of CD8 T lymphocytes in later stages of COVID-19." (PMID 33182268, 2020). "Other studies have confirmed the breadth of CD4 and CD8 T-cell responses in COVID-19 convalescent patients." (PMID 32875286, 2020). "The Spearman correlation analysis revealed that the presence of diabetes was positively correlated with age, hs-CRP, LDH, IL-6, CD8+ cells, and severity of COVID-19 and negatively correlated with CD3+ cell counts, CD4+ cell counts, and CD4+/CD8+ ratio." (PMID 33062712, 2020). "We then examined relationships between peak COVID-19 disease severity and neutralizing antibodies, SARS-CoV-2-specific CD4+ T cells, or SARS-CoV-2-specific CD8+ T cells across all cases." (PMID 33010815, 2020). "Therefore, it is interesting to compare results presented here to the clinical observation of depletion of pDCs, CD4+, and CD8+ T cells in severe COVID-19 patients, which are the exact cell types with complex morphologies that display high local levels of NGC." (PMID 41505524, 2026). "Additionally, stratification of the CXCR4+ T cells by CD4+ and CD8+ subsets showed that CD4+ T cell recruitment was much more abundant than CD8+ T cells, mirroring observations from COVID-19 lung infection studies." (PMID 41531734, 2026). "Both CD4+ and CD8+ Ki-67+ cells, along with hyperactivated (HLA-DR+CD38+) CD4+ T cells, showed significant increase, and CD4+ PD-1+ showed an increasing trend in COVID-19+ with culture." (PMID 40698364, 2025).
COVID-19 (continued). "There is a need to prioritize prevention, including prioritizing vaccine access, care and treatment of COVID-19 in PLHIV as recent studies have shown sufficient humoral response to vaccination regardless of low CD4 count." (PMID 41283262, 2025). "We found that overall hybrid immunity was associated with a significant reduction in the risk of COVID-19 and severe COVID-19 compared to vaccine immunity, but this effect did not seem to hold among PLWH with low CD4 counts or HIV viraemia." (PMID 39902315, 2025). "An example of a persistent immune response is seen in elderly individuals who survive severe COVID-19 and show a late increase in circulating CD4+, CD8+, and double-negative B cell populations." (PMID 41463036, 2025). "(2025) showed CD3+ T, CD4+ T, CD8+ T, and Treg cells reduced levels in COVID-19 patients." (PMID 41346576, 2025). "Testing included CD4 cell count, Xpert MTB/RIF Ultra assay (sputum), Determine TB LAM Ag assay (urine), chest X-ray, blood SARS-CoV-2 serology test and SARS-CoV-2 PCR (only if TB or COVID-19 symptoms)." (PMID 40267125, 2025). "A comparison between the COVID-19 and non-COVID-19 groups at the same time point revealed that the non-COVID-19 group exhibited significantly higher CD4+ T cell responses to the S, S1, and NMO antigens 4 weeks after the second booster." (PMID 41251472, 2025). "Our study shows that absolute counts of CD4+ T-lymphocyte functional subsets and CD8+ T-lymphocyte functional subsets are reduced in patients with COVID-19 compared to healthy controls, and the relative counts of Tregs are higher in patients with COVID-19, compared to healthy controls." (PMID 40988875, 2025). "Moreover, the lower frequencies of naïve CD4+ T cells and B cells in advanced NSCLC patients and COVID-19 patients compared with age-matched healthy volunteers is consistent with previous findings." (PMID 40308557, 2025). "Seven of the ten antigens were preferentially recognized by CD8+ and CD4+ T cells from unvaccinated asymptomatic COVID-19 patients, irrespective of VOC infection." (PMID 40894020, 2025). "Notably, we have previously identified cross-reactive memory CD4+, and CD8+ T-cell epitopes between common cold coronaviruses (CCCs) and SARS-CoV-2 in a study conducted on 147 unvaccinated COVID-19 patients." (PMID 40040708, 2025). "The percentage of ‘naive’ CD4+ T cells was decreased compared to patients without COVID-19; their absolute numbers were also lower than in the control group, suggesting reduced thymic output." (PMID 41376646, 2025). "However, there is a significant correlation between CD4+ PD-1 and CD8+ PD-1 in the patients with COVID-19." (PMID 40005306, 2025). "Numerous publications suggest that evaluating CD4+ and CD8+ T cell counts may provide significant prognostic information regarding the severity of COVID-19, including mortality, admission to intensive care units, and recovery." (PMID 40718799, 2025). "Using COVID-19 mRNA vaccination (BNT162b2/Comirnaty or mRNA-1273/Spikevax) and SARS-CoV-2 infection as model systems, we analyzed the robustness and longevity of vaccine-induced virus-specific CD4+ and CD8+ T cell immunity in INR versus IR." (PMID 41212052, 2025). "The relative counts of naïve CD4+ and naïve CD8+ T-lymphocytes were also reduced in patients in the COVID-19 group compared to healthy controls, whereas the relative counts of CD4+ memory T-lymphocytes, CD8+ memory T-lymphocytes, and Tregs were elevated in patients compared to healthy controls." (PMID 40988875, 2025). "Within COVID-19+, robust increases in the percentages of IFN-γ+CD4+TRM and IFN-γ+CD8+TRM in response to S peptide (8- and 50-fold, respectively, compared to 0 in controls) were noted only in subject #10 (female COVID-19+ with the shortest convalescence vaccinated at 27 days before tissue resection)." (PMID 40698364, 2025).
COVID-19 (continued). "According to the criteria for critical lung tissue damage incompatible with life, we conclude that HIV-positive patients with a reduction in CD4+ T cell counts of more than 60% from the initial level are unlikely to survive COVID-19." (PMID 40431602, 2025). "Overall, the highest frequencies of epitope-specific IFN-g-producing CD4+ and CD8+ T cells (determined as mean SFCs > 50 per 0.5 × 106 PBMCs fixed as threshold) were detected in the unvaccinated COVID-19 patients who developed less severe disease (i.e., severity 0, 1, and 2)." (PMID 40894020, 2025). "The CD4+ T cell count is considered an independent predictor of discordant immune responses among PLWH; it is crucial for inducing humoral immune responses to mRNA, adenovirus vector, and inactivated COVID-19 vaccines." (PMID 40838719, 2025). "A reduction in CD4+ CM cells and an increase in non-conventional monocytes (CD14lowCD16high) was, however, also present in post-COVID-19 conditions." (PMID 40766325, 2025). "People with HIV (PWH) experience a higher burden of non-HIV comorbidities, which predispose to more severe COVID-19, particularly in the setting of untreated HIV infection or low CD4+ T cell counts." (PMID 41041302, 2025). "Importantly, baseline reduction in both CD4+ and CD8+ EM cells were observed in COVID-19+ compared to UN individuals, and CD8+ EM cells tended to negatively correlate with convalescence." (PMID 40698364, 2025). "Although the presence of CD4+ T cells with a cytotoxic phenotype has been reported in both COVID-19 and TB, our study specifically identified that LTBI/COVID-19 individuals possess these unconventional CD4+ T cells, which appear to be entirely antigen-specific." (PMID 40458413, 2025). "In this study, differences in circulating activated CD4+ and CD8+ memory T cells among Black, Asian, and Caucasian subjects approximately 2 years after receiving a third dose of a COVID-19 vaccine (BNT162b2, mRNA-1273, ChAdOx1, or BBIBP-CorV) were investigated." (PMID 40573938, 2025). "Based on our results, we suggest that controlling high-severity-specific markers (FOS, CXCL8, HLA-A, JAK3, ICAM1, and H2BC4) and low-severity-specific markers (IL1B, CD3D, CD4, CCL5, and SNRPB) may prevent COVID-19 progression." (PMID 41155463, 2025). "No such correlations were detected among CD4+ T cells in patients with acute COVID-19, irrespective of the recruitment site." (PMID 39847442, 2025). "We found that early and robust SARS-CoV-2-specific CD4+ and CD8+ T cell responses ameliorate disease progression and shortened hospital stay, while delayed and attenuated virus-specific CD8+ T cell responses are prominent severe COVID-19 features." (PMID 38811527, 2024). "However, the antigen specificity, frequency, phenotype, and function of cross-reactive memory CD4+ and CD8+ T cells that protect against the severity of COVID-19 in unvaccinated asymptomatic patients remain to be determined." (PMID 38605956, 2024). "There is evidence to suggest that the frequency of lymphocyte subsets, particularly CD3+, CD4+, and CD8 + T cells, may have an inverse correlation with disease severity in COVID-19." (PMID 38355623, 2024). "Accordingly, we also detected low frequencies of functional CD134+CD137+CD4+ T cells and low frequencies of functional CD134+CD137+CD8+ T cells in unvaccinated severely ill COVID-19 patients and unvaccinated patients with fatal COVID-19 outcomes." (PMID 38605956, 2024). "In addition to antibody responses, the development of antiviral CD4+ and CD8+ T lymphocytes has been shown to improve survival in patients with COVID-19 and hematologic cancers." (PMID 39339993, 2024). "However, numerous studies have revealed significant impairments in the functioning of various immune cell types, including CD4+ T cells, CD8+ T cells, B cells, NK cells, monocytes, and other circulating, and resident cells in the COVID-19." (PMID 38921725, 2024).
COVID-19 (continued). "Although there was no statistical difference, post-COVID-19 and recent CD4 counts and CD4/CD8 ratios were slightly higher in vaccinated PWH." (PMID 39772028, 2024). "The role of blood levels of CD4+ Th cell subsets and their capacity to express related cytokines in the development of PCC and severe and critical forms of COVID-19 was analyzed by simple linear regression analysis and subsequent binary logistic regression analyses (OR)." (PMID 39257580, 2024). "Meanwhile, an increase of CD4+ T cells expressing CD69+ together with CCL5 levels was noted in our experiments using bLf on COVID-19 samples." (PMID 39483459, 2024). "Here, we used an activation-induced marker (AIM) assay to quantify SARS-CoV-2 spike-specific CD4+ and CD8+ T cells generated by two and three doses of COVID-19 vaccines in 50 PLWH receiving antiretroviral therapy, compared to 87 control participants without HIV." (PMID 38793543, 2024). "CD4 and CD8 T-cells have been detected in patients with COVID-19." (PMID 38699234, 2024). "Interestingly, we also noticed strong positive correlations between NK cell counts and both CD4+ T cell and CD8+ T cell counts in critical cases of COVID-19." (PMID 39650838, 2024). "In T cells, except for naïve CD4 + T cells, which showed a decrease at 6 months after recovery compared to 7 days, other CD4 + T cells and CD8 + T cells maintained higher levels at 6 months after COVID-19 recovery." (PMID 38844850, 2024). "Our study defines ex vivo SARS-CoV-2-specific T cells during primary and recall responses and provides key insights into CD8+ and CD4+ T cell responses in fully recovered and long COVID people, following SARS-CoV-2 infection and subsequent COVID-19 vaccination." (PMID 39284068, 2024). "Ki67 expressed by CD56dim NK cells, CD4+ T and CD8+ T cells didn't change after COVID-19." (PMID 39113896, 2024). "Following stimulation with OPs, CD4+ T cell responses were similar for both viral strains, with a significantly higher level of reactive CD4+ T cells compared with the negative control in the COVID-19-naïve group only." (PMID 39772110, 2024). "The reduced number of functional CCCs/SARS-CoV-2 cross-reactive memory CD4+ and CD8+ T cells detected in the peripheral blood of symptomatic COVID-19 patients may be due to T-cell redistribution to other organs, such as the lungs and the brain." (PMID 38605956, 2024). "In non-COVID-19 patients with GBS, P2 and—to a lesser extent—P0 were the main self-antigens targeted during the acute phase of the disease, whereas the autoreactive CD4+ T response was significantly increased against all three PNS-myelin antigens during the recovery phase." (PMID 38233524, 2024). "This transcript was also upregulated by CD4 memory T cells, dendritic cells, and ɣδ T cells in severe COVID-19 patients, while CD3 showed a lower expression rate across all cell types in sepsis and mild COVID-19 patients." (PMID 38892107, 2024). "In long COVID-19 patients, an increase of CD4+ and CD8+ T cells secreting IFN-gamma has been observed, and Cruz and co-authors found increased levels of both CD4+ and CD8+ T cells in long COVID-19 patients with lung sequelae." (PMID 38651389, 2024). "Patients with CD4/CD8norB+ had the quickest clearance of COVID-19, but there was no deference with patients with CD8domB+, CD4/CD8norBdep, or CD4domB+ subset." (PMID 38678181, 2024). "The highest number of DEGs that were specially upregulated in convalescents were detected in CD4+ naive T cells (290 DEGs), and these DEGs were not identified as upregulated DEGs in CD4+ naive T cells from COVID-19 naive individuals after vaccination." (PMID 38319108, 2024). "In specific, PD-1 expression in CD4+ T cells or CD8+ T cells was reduced in the COVID-19 convalescent patients, which was in line with the previous exploring T cells from patients 6 months post COVID-19 convalescence." (PMID 38424104, 2024).
COVID-19 (continued). "Previous studies, including several meta-analyses, also consistently report significantly lower counts of lymphocyte subsets CD4+ and CD8+ T-lymphocytes, NK-cells, and B-lymphocytes, along with a reduced total lymphocyte count in severely ill COVID-19 patients." (PMID 39691720, 2024). "Specific CD4+ T central memory (TCM), CD4+ effector memory (TEM), CD8+ TEM, and CD8+ terminal effector (TE) cells were all detectable and functional up to 12 months after the second dose of COVID-19 vaccines." (PMID 38793803, 2024). "The CD4/CD8 ratio was not statistically different between the two groups (4.0 ± 3.1 versus 3.6 ± 2.5 in the COVID-19+ and control group respectively, p = ns)." (PMID 38715114, 2024). "Age ≥40 years, CD4 count <200 cells/μL, having ≥2 comorbidities, and nonreceipt/incomplete SARS-CoV-2 vaccination increased severe COVID-19 risk among MWH in Catalonia." (PMID 38221982, 2024). "Regardless, there is no indication in our data that a low nadir CD4+ T-cell count impaired cellular responses to COVID-19 vaccination in our cohort." (PMID 38793543, 2024). "We compared the antigen specificity, frequency, phenotype, and function of CCCs/SARS-CoV-2 cross-reactive memory CD4+ and CD8+ T cells, cross-recognizing genome-wide conserved epitopes in a cohort of 147 unvaccinated COVID-19 patients, divided into six groups based on the severity of their symptoms." (PMID 38605956, 2024). "Additionally, it was observed that the counts of CD4+ T cells and CD8+ T cells have returned to normal levels in severe and critical cases of COVID-19 during the rehabilitation period." (PMID 39650838, 2024). "However, the interaction of people living with HIV–specific factors, such as CD4 cell count, HIV viral load, and antiretroviral treatment (ART), with COVID-19 remains inclusive." (PMID 38630534, 2024). "A number of immune cell analyses suggest that IFN-γ-producing CD4+ T, CD8+ T and NK cells are depleted in patients with severe COVID-19, which could plausibly explain the reduced IFN-γ plasma levels in ICU patients." (PMID 38399546, 2024). "We collected αβTCR repertoires of CD4+ T cells from multiple studies that isolated T cells from the peripheral blood of both COVID-19-positive and COVID-19-negative patients." (PMID 38615042, 2024). "In clinical trials, the first vaccines that utilized SARS-CoV-2 S proteins by mRNA lipoparticles (Pfizer BNT162b2; Moderna VRC mRNA) or viral vectored vaccines (CanSino AdV5 COVID-19; Oxford/AstraZeneca ChAdOx) indicated high efficiency for SARS-CoV-2-specific CD4+ and CD8+ T cells." (PMID 39568586, 2024). "Moreover, as the induction of an aged immune system, specifically senescent CD4 T cells, has been shown in mice to be sufficient to drive an aged phenotype, including frailty and multimorbidity, our data may also suggest broader implications for the health of COVID-19 survivors." (PMID 38212801, 2024). "Similarly, in one study, cell type-specific analysis revealed higher frequencies of CD39+ T cells in severe COVID-19 patients, while the expression of CD73 on CD4+ and CD8+ cells was reduced in the same group." (PMID 39519310, 2024). "In addition, the programmed death marker (CD279/PD-1) expression was diminished in bLf at 10 mg/mL for CD4+ and CD8+ T cells, but only in the COVID-19 group." (PMID 39483459, 2024). "Patients using immunosuppressive drugs prior to COVID-19 had significantly lower CD4+ T-lymphocyte counts compared to those who were not." (PMID 39691720, 2024). "Histopathological examination of GI tissues from COVID-19 patients revealed pronounced acute responses, especially in duodenal tissues, characterized by the predominant presence of inflammatory cells, specifically CD68+ macrophages and CD3+CD4+ T-cells." (PMID 39100091, 2024). "A similar trend was present in CD4 T cell responses; however, there were no strong differences in NK cell responses between severe COVID-19 and dengue disease." (PMID 38294906, 2024).